ALDH2 (aldehyde dehydrogenase 2 family member)
Diseases named in the same sentence as ALDH2 in open-access papers (continued):
Sharing a sentence is not in itself a finding about the gene and the disease.
alcoholic liver diseases (7 papers, 2015 to 2025). A disorder caused by damage to the liver parenchyma due to alcohol consumption. "Therefore, the ALDH2 rs671 polymorphism not only increases the risk of HCC recurrence in alcoholic liver disease-related HCC patients after resection but also poses a risk for HCC recurrence in patients with MAFLD-related HCC after resection." (PMID 40660548, 2025). "Investigating if MitoQ could preserve mitochondrial ALDH2 activity and speed up acetaldehyde clearance, thereby protects against alcoholic liver disease." (PMID 40134978, 2025). "ALDH2 gene enrichment in Alcoholic liver disease, Pantothenate and CoA biosynthesis pathways." (PMID 38609879, 2024). "Among the top 30 genes in the gene regulatory network, 7 genes are enriched in alcoholic liver disease (hsa04936), including TNF, IL6, IFNA1, CYP2E1, ALDH2, ADH1B, ADH1C." (PMID 38429802, 2024).
Anxiety (7 papers, 2012 to 2023). Intense feelings of nervousness, tension, or panic often arise in response to interpersonal stresses. "Meanwhile, Glo1, G6pdx, Aldh2, and Dld were distinctly dysregulated in the anxiety-susceptible group." (PMID 31624233, 2019). "In the anxiety-susceptible group, Glo1, G6pdx, and Aldh2 were significantly down-regulated, while Dld was up-regulated, when compared to the control group." (PMID 31624233, 2019). "More recently, ALDH2 inhibitors have been shown to reduce anxiety associated with treatment of cocaine and alcohol addiction." (PMID 22840776, 2012). "We investigated whether variation in genes encoding cytochrome P450 2E1 (CYP2E1) or acetaldehyde-metabolising enzymes (ALDH1A1, ALDH2) might alter the risk of AD, with and without symptoms of anxiety, in a Cape population with mixed ancestry." (PMID 24567230, 2014).
cardiomyopathy (7 papers, 2016 to 2024). A disease of the heart muscle or myocardium proper. "In an effort to examine the possible mechanism of action involved in ALDH2-offered response to insulin resistance-associated cardiomyopathy, if any." (PMID 27634872, 2016). "Taken together, our data suggest that ALDH2 serves as an indispensable cardioprotective factor against insulin resistance-induced cardiomyopathy with a mechanism possibly associated with facilitation of the Sirt3-dependent PGC-1α deacetylation." (PMID 27634872, 2016). "Data from our current study revealed that ALDH2 counteracts insulin resistance-induced cardiomyopathy (myocardial, cardiomyocyte function and intracellular Ca2+ handling) possibly in association with regulation of Sirt3 and mitochondrial integrity." (PMID 27634872, 2016). "Further study is warranted to unveil the mechanism behind ALDH2-mediated Sirt3 deacetylation in a more clinically relevant setting of insulin resistance-induced cardiomyopathy." (PMID 27634872, 2016). "Several molecules designed by targeting heme oxygenase-1 and mitochondrial aldehyde dehydrogenase (ALDH2) may serve as activators of AMPK, recovering normal autophagic activity and protecting from cardiomyopathy." (PMID 35783195, 2022). "Since CYP2E1 and ALDH2 are expressed in the heart, future studies of the opposite regulation of CYP2E1 (i.e., induction) and ALDH2 (i.e., suppression) during the alcohol-mediated production of MDA and/or 4-HNE adducts and the consequent cardiomyopathy would be of interest." (PMID 33568752, 2021).
ovarian carcinoma (7 papers, 2018 to 2023). A malignant neoplasm originating from the surface ovarian epithelium. "Along this thought of line, we would have expected to see a high OS in East Asian women with ovarian cancer because their ALDH2 activity would be zero in ALDH2 mutation carriers." (PMID 29552329, 2018). "The present analysis also examined ovarian cancer risk using the functional ALDH2 rs671 polymorphism." (PMID 29247577, 2018). "In this review, we use the evidence from literature, transcriptomic data with average 5-year overall survival to suggest that the key factor that determines the low incidence and mortality of ovarian cancer in East Asian women is the ALDH2 mutation." (PMID 29552329, 2018). "The strengths of this investigation include the analysis of individual‐level data from a relatively large sample compared to previous studies, which allowed us to quantify risk associations of the ALDH2 polymorphism, detailed drinking status and ovarian cancer risk." (PMID 29247577, 2018). "The aldehyde dehydrogenase 2 (ALDH2) polymorphism rs671 (Glu504Lys) causes ALDH2 inactivation and adverse acetaldehyde exposure among Asians, but little is known of the association between alcohol consumption and rs671 and ovarian cancer (OvCa) in Asians." (PMID 29247577, 2018). "Another piece of evidence to support ALDH2’s role in ovarian cancer is that the risk of ovarian cancer goes up with age, and ALDH2*2 homozygous genotype was significantly reduced in females in the 60–70s age group versus 40–50s group in a study with more than 2,200 Japanese." (PMID 29552329, 2018). "To investigate whether there is an association between alcohol drinking, the rs671 polymorphism in ALDH2 and ovarian cancer risk, we conducted a pooled analysis of data from women of Asian ancestry participating in the Ovarian Cancer Association Consortium (OCAC)." (PMID 29247577, 2018). "It is notable to see that ALDH2 expression is at very high level in stem-like tumor cells of ovarian cancer, indicating that a high ALDH2 activity of stem cells renders significant influence on the morbidity and mortality of ovarian cancer." (PMID 29552329, 2018). "We notice that East Asian population usually are inactive aldehyde dehydrogenase 2 mutation (ALDH2*2) carriers, and ALDH plays an important role in the resistance of ovarian cancer to chemotherapeutics, especially in ovarian cancer stem cells." (PMID 29552329, 2018). "As can be seen, the expression of ALDH1A1 and ALDH2 vary in different cancers, as well as between ovarian cancer PTC and TSC." (PMID 29552329, 2018). "Very interestingly and curiously, the relationship between ALDH2 and ovarian cancer has drawn little attention." (PMID 29552329, 2018). "Taken all the references together, it is highly likely that the very low incidence rate and the lowest mortality rate of ovarian cancer in East Asian women is mainly due to the fact that many East Asian women are ALDH2*2 carriers." (PMID 29552329, 2018). "Therefore, we hypothesize whether ALDH2 mutation is the major reason for low incidence and mortality of ovarian cancer in East Asian women, and use the evidence from literature, transcriptomic data with average 5-year overall survival to confirm our hypothesis." (PMID 29552329, 2018). "Ideally the best way to test our reasoning and rationale is to compare the ALDH2 activity in ovarian cancer stem cells with the killing rate of chemotherapy for ovarian cancer stem cells or compare the ALDH2 activity in ovarian stem cells with the ovarian cancer incidence." (PMID 29552329, 2018). "For further demonstration of the ovarian cancer microenvironment, we have investigated cancer stem cells expressing CD44, LGR5 and ALDH2." (PMID 36604635, 2023). "Although a huge amount studies have been done to compare East Asian women with Caucasian women with respect to various diseases, there is no study conducted on ovarian cancer with respect to ALDH2." (PMID 29552329, 2018).
ovarian carcinoma (continued). "In addition, mitochondrial phosphoproteomics and immunoprecipitation-western blot experiments identified and confirmed that phosphorylation occurred at residue Ser70 in protein HSP60, which might regulate protein folding of ALDH2 and ACADS in ovarian cancers." (PMID 34557266, 2021).
steatosis (7 papers, 2015 to 2023). Increased lipid within the cytoplasm of cells. "Many in vivo experiments have confirmed that ALDH2 efficiently increases the survival rate of ethanol-fed mice by inhibiting ethanol-induced inflammatory responses and steatosis." (PMID 37143126, 2023). "Using biochemistry data, abdominal ultrasonography, fibrosis evaluation (Kpa), and steatosis evaluation (CAP), ADH1B gene SNP rs1229984 and ALDH2 gene SNP rs671 polymorphism were analyzed in sixty-six patients from 1 January 2022 to 31 December 2022." (PMID 37240928, 2023). "In the same study, further administration of the ALDH2 agonist Alda-1 reduced the acetaldehyde level and promoted FA oxidation in the liver, effectively ameliorating steatosis in the mice." (PMID 37143126, 2023). "The associations between metabolic factors, BMI, serum alanine transaminase (ALT), histological steatosis or fibrosis, and ADH1B/ALDH2 gene polymorphism were also analyzed." (PMID 37240928, 2023). "Moreover, ALDH2 overexpression exerts protective effects against chronic alcohol intake-induced hepatic injuries, including acetaldehyde accumulation, steatosis and inflammation." (PMID 35713687, 2022).
alcohol addiction (6 papers, 2012 to 2024). "ALDH2 was first associated with the flush that occurs on the face when a person consumes alcohol and alcohol addiction." (PMID 25313998, 2014). "Until now, it is an intriguing issue that the subjects with ALDH2*2 gene allele could override the physiological barrier to develop alcohol addiction." (PMID 34439848, 2021). "Mitochondrial aldehyde dehydrogenase (ALDH2) is a potential target for the treatment of substance use disorders such as alcohol addiction." (PMID 36557906, 2022).
bladder cancer (6 papers, 2018 to 2022). "It is also known that DSF, an inhibitor of ALDH2, reduces the risk of bladder cancer in rats exposed to nitrosamines." (PMID 34940794, 2022). "The aim of this study was to examine the association between alcohol drinking and bladder cancer risk using data from ten population-based prospective cohort studies in Japan, where approximately 40% of the population has inactive ALDH2 enzyme." (PMID 31204364, 2020). "The present null result may, therefore, suggest the need for future studies that investigate bladder cancer risk associated with alcohol consumption stratified by the ALDH2 and ADH1B polymorphisms in East Asians." (PMID 31204364, 2020). "To address this hypothesis, we examined the association of alcohol drinking with bladder cancer from a pooled analysis of ten population-based cohort studies in Japan, where approximately 40% of the population has inactive ALDH2 enzyme, despite some variation across areas." (PMID 31204364, 2020). "Given that the inactive ALDH2 alleles are specific to East Asian populations, alcohol drinking may have a strong effect of bladder cancer risk in East Asian populations compared with Western populations, implying carcinogenic effects of alcohol-related acetaldehyde on the bladder." (PMID 31204364, 2020).
fibrosis (6 papers, 2016 to 2025). the formation of excess fibrous connective tissue in an organ or tissue in a reparative or reactive process. "In vitro and in vivo studies demonstrate that ALDH2*2 amplifies oxidative stress and disrupts mitochondrial homeostasis under hyperglycemic conditions, leading to enhanced cardiac fibrosis and functional decline." (PMID 40564981, 2025). "Additionally, mitochondrial ATP levels were markedly reduced in the kidneys of ALDH2-mutant mice across both fibrosis models." (PMID 39226171, 2024).
glioma (6 papers, 2019 to 2025). A benign or malignant brain and spinal cord tumor that arises from glial cells (astrocytes, oligodendrocytes, ependymal cells). "Other loci were found altered such as Aldehyde dehydrogenase 2 (ALDH2) and isocitrate dehydrogenase 2 (IDH2), that was found to predispose to cervical carcinoma and glioma respectively as well as BCL3, AKT2 and ERCC2 for which polymorphisms were shown to be associated with lung carninoma." (PMID 31105870, 2019). "Six genes of these essential TrMGs, including MAOB, HSD17B10, KYNU, AOX1, and OGDH, were determined as hazardous factors for glioma patients, and other two genes (CYP2E1 and ALDH2) were identified as protective factors." (PMID 36386216, 2022). "In the LGG cohort from the TCGA dataset, ALDHs including ALDH2, ALDH6A1, ALDH5A1, ALDH9A1, ALDH1A1 were upregulated in WHO grade II gliomas while the increased expression of ALDH16A1, ALDH3B1, ALDH3A2, ALDH1A2, ALDH3A1 was found in WHO III grade gliomas." (PMID 35116021, 2021). "Analysis of the TCGA dataset showed that ALDH16A1, ALDH3B1, ALDH1A3, ALDH3A1, ALDH7A1 were significantly increased in IDH wildtype gliomas, while ALDH2, ALDH6A1, ALDH5A1, ALDH1A1, ALDH1L2, ALDH18A1, ALDH1B1 expression were higher in IDH mutant gliomas than IDH wildtype gliomas." (PMID 35116021, 2021). "The results of IHC demonstrated that the expression level of KYNU was higher in high-grade glioma compared to low-grade glioma, and the expression level of ALDH2 was higher in low-grade glioma, confirming the results from sequencing that KYNU was hazardous factor and ALDH2 was protective factor." (PMID 36386216, 2022).
oropharyngeal cancer (6 papers, 2015 to 2022). Carcinoma, predominantly squamous cell, arising from the epithelial cells of the oropharynx. "The oropharyngeal cancer risk of ALDH2-deficient alcohol drinkers compared with that of ALDH2-active individuals thus appears to have a dose-dependent correlation with the additional local ACH exposure caused by the deficient ALDH2 enzyme." (PMID 29303995, 2018). "According to one meta-analysis and one well-performed study (total of 1189 cases and 3239 controls), ALDH2 deficiency is associated with a 1.68-fold to 2.61-fold oropharyngeal cancer risk in moderate drinkers and 3.57-fold to 7.28-fold risk in heavy drinkers." (PMID 29303995, 2018). "The purpose of this study was to investigate the possibility of ALDH2 polymorphism as a prognostic factor for oropharyngeal cancer (OPC) among Japanese population." (PMID 29206831, 2017). "Noteworthy, many epidemiological studies showed the ALDH2 deficiency gene (ALDH2*2 allele) to be associated with markedly increased risk of digestive tract cancers, including oro-pharyngeal cancers, even after a moderate dose of alcohol intake." (PMID 26225960, 2015). "In Japan, HPV-negative oropharyngeal cancer patients with the ALDH2 heterozygous genotype had significantly poorer 3-year overall survival rate and disease-specific survival rate than the ALDH2 homozygous genotypes." (PMID 35330099, 2022). "One possible explanation is that patients with heterozygous ALDH2 might continue to drink alcohol at a higher level even after the treatment of oropharyngeal cancer." (PMID 29206831, 2017). "However, ALDH2 gene was expressed in high (p = 0.03) levels in patients with oropharyngeal cancers or laryngeal cancers." (PMID 28841898, 2017).
viral infection (6 papers, 2020 to 2025). "It is known that chronic HBV or HCV infection is common in the Asian continent; adjustment for viral infection may be necessary to clarify whether potential interactions between ALDH2 rs671 and alcohol drinking contribute to HCC susceptibility." (PMID 31987047, 2020). "Our results also demonstrated a positive correlation between ALDH2 levels and the presence of tumor-infiltrating B cells (TIL-Bs), essential adaptive immune cells often found in cancers caused by carcinogens and viral infections." (PMID 37476181, 2023).
asthma (5 papers, 2017 to 2025). "In addition, ALDH2 plays a protective role in the inflammatory damage caused by reactive oxygen species, which is known to be related with aggravated airway damage in asthma." (PMID 36076228, 2022). "In humans, the ALDH2*2 allele was associated with lower FEV1/FVC in the general population, but not with the development of asthma or COPD." (PMID 28431562, 2017). "We found that human carriers of the loss-of-function ALDH2*2 allele presented significantly lower FEV1/FVC than individuals who have the ALDH2/ALDH2 allele, but that was not accompanied with lower predicted FEV1%, faster rate of annual FEV1 decline, or asthma/COPD." (PMID 28431562, 2017).
cerebral infarction (5 papers, 2015 to 2025). An ischemic condition of the brain, producing a persistent focal neurological deficit in the area of distribution of the cerebral arteries. "Our research group previously obtained a novel class of N-benzylaniline-based ALDH2 activators through virtual screening and preliminary structural optimization, which have a protective effect on animal models of cerebral infarction." (PMID 40733191, 2025). "In contrast, information regarding the relationship between the ALDH2 SNP and brain infarction is scarce." (PMID 26599441, 2015). "In contrast, myocardial and brain infarctions were significantly increased in ALDH2 *2 carriers compared with that in the lifetime abstainers with ALDH2 *1/*1, irrespective of drinking status." (PMID 26599441, 2015). "In contrast, myocardial and brain infarction prevalence was significantly increased in ALDH2 *2 carriers compared with that in the lifetime abstainers with ALDH2 *1/*1, irrespective of drinking status." (PMID 26599441, 2015).
dementia (5 papers, 2019 to 2025). Loss of intellectual abilities interfering with an individual's social and occupational functions. "Some research teams have reported that patients with T2DM and mutations in the formaldehyde (FA)-degrading enzyme aldehyde dehydrogenase 2 (ALDH2) gene have higher levels of FA and more severe dementia." (PMID 37189611, 2023). "So, will increased global alcohol consumption, along with a large ALDH2 polymorphic drinking population, spur an increase in dementia patients?" (PMID 37693648, 2023). "We investigated the association between the ALDH2 rs671 variant and MCI using data from the Brain MRI Checkup Cohort, consisting of Japanese residents who were independent in their activities of daily living and without apparent dementia." (PMID 39401906, 2024). "LNX2 and ALDH2 may be potential genetic markers and new targets for the diagnosis and treatment of MCI and T2DM, which are promising for delaying the occurrence and development of dementia." (PMID 37189611, 2023). "Significantly associated proteins at a false discovery rate (FDR) < 0.05 in both models 1 and 2 were CGREF1, MET, ALDH2, NECTIN2, APOC1, APOE and FOSB for HFRS, and CDK and POF1B for HFRS without dementia." (PMID 40764432, 2025).
infarction (5 papers, 2015 to 2026). A localised pathological necrosis of tissue resulting from obstruction of the blood supply usually by a thrombus, an embolus, or vascular torsion. "ALDH2 protein and mRNA expression on infarction border zone was significantly and similarly decreased at 1 week, 2 weeks, and 3 weeks after MI (all P < 0.05 versus Sham)." (PMID 25629048, 2015). "We found that Tan I improved post-infarction cardiac function and myocardial injury, inhibited post-infarction collagen deposition and EC ferroptosis, and promoted CD31 expression in vivo by activating ALDH2 and promoting ALDH2 signaling-related protein levels." (PMID 40642000, 2025).